CD8B (CD8 subunit beta)
Description:
Integral membrane glycoprotein that plays an essential role in the immune response and serves multiple functions in responses against both external and internal offenses. In T-cells, functions primarily as a coreceptor for MHC class I molecule:peptide complex. The antigens presented by class I peptides are derived from cytosolic proteins while class II derived from extracellular proteins. Interacts simultaneously with the T-cell receptor (TCR) and the MHC class I proteins presented by antigen presenting cells (APCs). In turn, recruits the Src kinase LCK to the vicinity of the TCR-CD3 complex. A palmitoylation site in the cytoplasmic tail of CD8B chain contributes to partitioning of CD8 into the plasma membrane lipid rafts where signaling proteins are enriched. Once LCK recruited, it initiates different intracellular signaling pathways by phosphorylating various substrates ultimately leading to lymphokine production, motility, adhesion and activation of cytotoxic T-lymphocytes (CTLs). Additionally, plays a critical role in thymic selection of CD8+ T-cells.
Synonyms: CD8B1; Ly-3; LYT3; P37; CD8beta; LEU2; LY3
Tractability: Antibody: UniProt places it where antibodies can reach, with high confidence; its Gene Ontology location is reachable by antibodies, with high confidence; UniProt predicts a signal peptide or a membrane-spanning region; the Human Protein Atlas places it where antibodies can reach.
Gene: Protein-coding gene on chromosome 2 (86,815,339 to 86,861,934, reverse strand). Ensembl gene ENSG00000172116.
Subcellular location: Cell membrane (Isoform 1); Cell membrane (Isoform 2); Secreted (Isoform 3); Cell membrane (Isoform 4); Cell membrane (Isoform 5); Secreted (Isoform 6); Secreted (Isoform 7); Secreted (Isoform 8)
Subcellular location (Human Protein Atlas): Plasma membrane
Pathways (Reactome):
Disease: Nef Mediated CD8 Down-regulation
Immune System: Immunoregulatory interactions between a Lymphoid and a non-Lymphoid cell
Gene Ontology:
Molecular function: protein binding; coreceptor activity; MHC class I protein binding
Biological process: T cell activation; T cell receptor signaling pathway; adaptive immune response; cell surface receptor protein tyrosine kinase signaling pathway; immune response; regulation of immune response
Cellular component: plasma membrane; early endosome membrane; T cell receptor complex; extracellular region
Genetic constraint (gnomAD): Loss-of-function variants: 6 observed, 15.51 expected, observed/expected ratio (o/e) 0.39, 90% interval 0.21 to 0.76. The upper end of that interval is the gene's LOEUF score, 0.76, which puts it in group 3 of 6, group 1 being the genes least tolerant of losing a copy. Missense variants: 189 observed, 222.5 expected, observed/expected ratio (o/e) 0.85, 90% interval 0.75 to 0.96. Synonymous variants: 81 observed, 84.37 expected, observed/expected ratio (o/e) 0.96, 90% interval 0.8 to 1.15.
Homologues: Orthologues: chimpanzee CD8B (98% identical), macaque CD8B (86% identical), dog CD8B (68% identical), pig CD8B (60% identical), guinea pig Cd8b (60% identical), rat Cd8b (54% identical), mouse Cd8b1 (53% identical), zebrafish cd8b (20% identical). Paralogues in human: CD8B2 (98% identical).
Diseases named in the same sentence as CD8B in open-access papers:
CD8B is named in the same sentence as 70 diseases in open-access papers, as found by Europe PMC text mining. Sharing a sentence is not in itself a finding about the gene and the disease. The quoted sentences say what the papers report.
lymphoma (16 papers, 2009 to 2025). A malignant (clonal) proliferation of B- lymphocytes or T- lymphocytes which involves the lymph nodes, bone marrow and/or extranodal sites. "IL-10 expression did not significantly differ between subtype infection profiles but did show a marked increase—accompanying decreased CD4:CD8b ratio—in a koala with lymphoma and co-infected with KoRV-A and -B, thus suggesting immunosuppression." (PMID 33316950, 2020). "Further investigation of a KoRV-B- and C-positive adult koala that died (found to have lymphoma) revealed immunosuppression characterized by a decreased CD4:CD8b ratio and increased IL-10 expression." (PMID 33316950, 2020). "CD4:CD8b ratio in unstimulated koala PBMCs was markedly higher in the KoRV-B-positive, KoRV-C-negative individual (KM, which showed lymphoma) than in koalas with endogenous infection only (KoRV-A); however, this ratio showed no other significant differences between KoRV subtype infection profiles." (PMID 33316950, 2020). "Other specific feline antibodies (anti-CD4, anti-CD8α, anti-CD8β) can be used to detect additional epitopes and define the immunophenotype of lymphomas, but their routine clinical application is limited by the fact that formalin-fixed samples cannot be used as frozen sections are required." (PMID 30305106, 2018). "However, as might be expected based on previous research in koalas, the KoRV-A- and B-positive koala with lymphoma that died in this study showed a markedly decreased CD4:CD8b ratio and markedly increased IL-10 expression." (PMID 33316950, 2020). "We thus propose CD8β as a new marker to include in the classification of patients with γδ T-ALL, and urge the phenotypic assessment of its expression within human γδ T cells in other leukemia and lymphoma cohorts, as well as in other diseases." (PMID 38802512, 2024).
melanoma (16 papers, 2013 to 2025). A malignant, usually aggressive tumor composed of atypical, neoplastic melanocytes. "Notably, the combined expression of CCR9, CCL25, CD8A, and CD8B genes in tumors positively correlated with a higher DSS probability in patients with melanoma, with a better hazard ratio (HR) and P value compared to the expression of CD8A and CD8B genes only." (PMID 41042869, 2025). "And the negative correlation between 6 ICD-related genes (CD8A, PRF1, IFNG, CXCR3, TNF, CD8B) and risk score and the protective function of these 6 genes in SKCM indicates that drugs targeting these genes may be a novel treatment method in melanoma." (PMID 36211436, 2022). "Our data revealed heightened expression of CD8+ T cell markers (CD8a and CD8b) and NK cell markers (NCR1 and NCR3) in melanoma patients with elevated levels of cGAS/CCL5/CXCL10." (PMID 38506049, 2024). "To further validate the functional relevance of tumor-enriched populations, we performed IL-1β-enriched NT GSDMD treatment of B16F10 melanoma in immunocompetent C57BL/6 mice with depleted NK1.1 and CD8β-expressing cells." (PMID 39737979, 2024). "All phenotypic and functional markers of T cells—CD3E, CD4, CD8B, FOXP3, GZMB, PRF1 and TBX21—were expressed at higher levels in melanoma patients with high ETV7 expression." (PMID 33424867, 2020). "That neither TRBC2, CD4 nor CD8B expression within melanomas was predictive of a response to CPI therapies also supports a bona fide association of response with Vδ1+ cells." (PMID 38172341, 2024). "In the example of a melanoma BrM tissue section where tumor parenchyma was surrounded by inflammatory stroma (patient 16), densities of CD3E, CD4, CD8A, and CD8B transcripts were highest in the peritumoral inflammation and in the directly adjacent tumor parenchyma." (PMID 35584630, 2022). "As the aim of this work was to understand how melanoma TME affects the infiltration of CD8+ T cells, we excluded CD8+ T cell specific markers (CD8A, CD8B, GZMK and NKG7), as well as genes expressed in most CD8+ T cells (more than 50%) but in less than 10% of the remaining cells in the melanoma TME." (PMID 34040608, 2021). "In addition to the purity check upon cell sorting, potential CTL contamination in melanoma cell samples isolated from the co-cultures was checked by including a series of CTL markers on the NanoString (CD3D, CD3E, CD3G, CD8A and CD8B)." (PMID 27625650, 2016). "Purified CD4+ T cells were stimulated with beads coated with anti-CD3 and anti-CD28 antibodies and co-transduced with a lentivirus expressing codon-optimized CD8α and individual CD8β isoforms and a second lentivirus expressing TCRαβ from a CD8 dependent TCR recognizing the melanoma antigen NY-ESO-1." (PMID 23533620, 2013).
Sepsis (6 papers, 2016 to 2023). Sepsis is defined as life-threatening organ dysfunction caused by a dysregulated host response to infection. "Dot plot of these genes in sepsis single-cell data revealed the CD8+ T cell exhaustion subcluster (TS3 with high CD8+ T cell markers CD8a, CD8b, and exhaustion markers PDCD1 and CTLA4)." (PMID 37077915, 2023). "A similar finding was found in HIV-infected patients with sepsis, who showed overexpression of genes involved in cytotoxic T-cell signaling (CD8A, CD8B)." (PMID 34497613, 2021). "HIV positive sepsis patients in both ICU cohorts showed overexpression of genes involved in granzyme signaling (GZMA, GZMB), cytotoxic T-cell signaling (CD8A, CD8B) and T-cell inhibitory signaling (LAG3), compared to HIV negative patients." (PMID 26871709, 2016). "Cytotoxic T-cell signaling (CD8A, CD8B) and T-cell inhibitory signaling (LAG3) were overexpressed in HIV patients both during sepsis and in asymptomatic HIV infection." (PMID 26871709, 2016). "In HIV negative sepsis patients, a reduction in CD8A and CD8B is consistent with immune suppression, which is considered an integral part of the host response to sepsis, and also involves enhanced apoptosis of CD8 T cells." (PMID 26871709, 2016). "Principal component analysis of GZMA, GZMB, CD8A, CD8B, KLRD1, PRF1 and LAG3 gene expression revealed 81% explained variance for the first principal component considering HIV negative and HIV positive sepsis patients." (PMID 26871709, 2016).
breast carcinoma (5 papers, 2021 to 2024). "Lee found that CD8B gene expression was closely correlated with tumor-infiltrating lymphocytes (TILs) in breast cancer." (PMID 35739510, 2022). "We found that SLAMF6 expression was highly correlated not only with the expression of T-cell markers (CD3E, CD8B, CD8A, and CD4) but also with upregulation of TCF7, PDCD1 encoding PD-1, GZMK, and effector-associated genes including IFNG and PRF1 in breast cancer." (PMID 38287061, 2024). "The genes sharing these GO terms have been previously shown to be involved in breast cancer prognostic process (e.g., CXCR6, KIT, RUNX3) and also immune cell regulation (e.g., CD8B, DAPP1, LY75)." (PMID 33919884, 2021). "Interestingly, expression of some immune cell genes and DVL-1 uniquely correlated with luminal breast cancer, such as CD19, CD79A, CD8B, CCR7, CD1C, and STAT5B." (PMID 34659647, 2021). "Consequently, CD8+ T-cell effector (Teff) score, comprising gene expression of IFNG, PRF1, CD8A and CD8B, and BATF3-DC score, calculated with the expression level of BATF3, IRF8, THBD, CLEC9A, and XCR118 were markedly increased in the high SLAMF6 group than in the low SL AMF6 group in breast cancer." (PMID 38287061, 2024).
viral infections (4 papers, 2012 to 2025). "In support of this notion, it has previously been reported that CD8α/CD8β expression corresponds to cytotoxic lymphocyte activity in carp, allogeneic stimulation in rainbow trout, as well as virus infection in salmon." (PMID 22529969, 2012). "Thus far, porcine CD8β+ T cells are considered to have a cytolytic function and to be involved in protective immunity against viral infections." (PMID 41250130, 2025). "CD8 glycoprotein, composed of CD8α and CD8β subunits, is expressed on CD8+ cytotoxic T lymphocytes and CD8+ regulatory T cells, which are crucial for host immune responses against viral infections and cancer cells." (PMID 38020762, 2023). "Similarly, the observed expansion of CD8β+ T cells in the blood of three animals following FLUAVsw infection might indicate that also this T-cell subset was already in a maturation stage enabling a reaction to this viral infection." (PMID 25971313, 2015).
lung adenocarcinoma (3 papers, 2021 to 2025). A carcinoma that arises from the lung and is characterized by the presence of malignant glandular epithelial cells. "In the two-sample Mendelian randomization (MR) analysis, it was observed that RNF125, CD8B, and TRGV9 exhibit no heterogeneity concerning lung adenocarcinoma (LUAD)." (PMID 38297377, 2024). "Lastly, although the authors observed inverse correlations between EPHA2 and CTL gene signatures in human pancreatic cancer, we did not discover any consistent trends between EPHA2 and CD3E, CD8B, GZMA, GZMB, PRF1, or IFNG expression from the TCGA lung adenocarcinoma dataset." (PMID 40867322, 2025).
osteoarthritis (3 papers, 2021 to 2024). A noninflammatory degenerative joint disease occurring chiefly in older persons, characterized by degeneration of the articular cartilage, hypertrophy of bone at the margins and changes in the synovial membrane. "CD8b influences osteolysis and the immune response in osteoarthritis, impacting osteoclast formation." (PMID 38459548, 2024). "Even two shared lncRNA–mRNA interaction pairs in osteoarthritis and osteolysis (AC111000.4 and AC016831.6) may function in the immune process of osteoarthritis and osteolysis by regulating lymphocyte CD8A and CD8B, respectively." (PMID 38106424, 2023).
primary immunodeficiency (3 papers, 2016 to 2022). "The analysis of the altered pathways related to these genes showed the only significant KEGG pathway identified was “primary immunodeficiency pathway” (q-value <0.05), with three SDE genes upregulated (CD8A, CD8B, and TNFRSF13C) in HIV/HCV-f." (PMID 34497613, 2021).
skin cutaneous melanoma (3 papers, 2022 to 2023). "Analysis of TCGA RNAseq data from cutaneous melanomas established that mRNAs encoding the CD8 T cell coreceptor subunits CD8α and CD8β have strong positive correlations with CD47 mRNA expression." (PMID 36768931, 2023). "We next assessed the survival and expression of NK cell markers (NCR1 and NCR3) and CD8 T cell markers (CD8A and CD8B) in 448 patients with skin cutaneous melanoma reported in the TCGA database." (PMID 36458012, 2022).
atherosclerosis (2 papers, 2013 to 2022). A disease characterized by the build-up of fatty material and calcium deposition in the arterial wall resulting in partial or complete occlusion of the arterial lumen. "In agreement with inhibition of the aortic recruitment of pro-inflammatory T cells by captopril, ACE inhibitor treatment with captopril prevented the atherosclerosis-related increase in the aortic content of the T cell-specific Cd8b protein of ApoE−/− mice as determined by immunoblotting." (PMID 23801967, 2013). "We focused on targeting CD8β chain with specific antibodies and also via genetic deletion and have previously used such a strategy to define the role of CD8+ T cells in atherosclerosis." (PMID 36483558, 2022). "In contrast, vitamin E treatment did not significantly change the amount of Cd8b protein in the atherosclerosis-prone aorta of ApoE−/− mice compared to untreated ApoE−/− mice." (PMID 23801967, 2013).
colitis (2 papers, 2021). Inflammation of the colon. "In males, Cd8b and then Ifng expression in the SNpc were the next factors most highly associated with TH followed by colitis DAI score, Tnf in the SNpc, and TNF in plasma." (PMID 34412704, 2021). "Acute DSS colitis significantly increased expression of Lcn2, Ptprc, Cd8b, and Snca in the colon of male mice and of Lcn2 in female mice." (PMID 34412704, 2021). "Indeed, this study found increased Cd8b expression in colon tissue of male mice following acute colitis but more modest changes in females which only reached statistical significance in females lacking RGS10." (PMID 34412704, 2021).
colon adenocarcinoma (2 papers, 2024). "The Cancer Genome Atlas (TCGA)-colon adenocarcinoma (COAD) dataset was also analyzed to identify cytotoxic T lymphocyte (CTL) scores using a set of 5 previously reported genes (CD8A, CD8B, GZMA, GZMB, and PRF1) as a surrogate of tumor infiltrating CD8+ T cells." (PMID 38992029, 2024). "In addition, the positive correlations between ZC3H12C expression and highly connected CD8+ T genes were also visualized, including CD8A, CD8B, GZMA, GZMB, and PRF1 in colon adenocarcinoma and rectum adenocarcinoma." (PMID 38267865, 2024).
esophageal carcinoma (2 papers, 2023 to 2024). A primary or metastatic malignant neoplasm involving the esophagus. "Furthermore, ENTPD1 expression in esophageal carcinoma tissues was positively correlated with the expression of genetic markers of multiple TIICs, including CD8A and CD8B of CD8+ T cells, with or without adjustment for tumor purity." (PMID 36831526, 2023).
Granuloma (2 papers, 2019 to 2025). A compact, organized collection of mature mononuclear phagocytes, which may be but is not necessarily accompanied by accessory features such as necrosis. "The low number (n = 2) of CD8β-depleted animals that formed granulomas precludes meaningful conclusions being drawn for that group." (PMID 39912921, 2025). "CD8β-depleted animals had very few granulomas at necropsy, similar to undepleted animals (median: 0)." (PMID 39912921, 2025). "We observed that granulomas showed co-expression of Inos and different T-cell-related transcripts (Cd3e, Tcrb, Cd8b) at 3 wpi." (PMID 31015452, 2019). "In addition, the small number of granulomas obtained from the CD8β-depleted group limited our analysis of these samples." (PMID 39912921, 2025). "The density of several transcripts including Ccr6, Cd19, and Il12, and to a lesser degree Cd3e, Cxcr3, and Cd8b mRNA was increased in the lymphoid in relation to the epithelioid areas after a supervised annotation of the lymphoid and the epithelioid areas of the granulomas based on H&E staining." (PMID 31015452, 2019). "The number of cells in granulomas did not change following CD4 or CD8β depletion but significantly increased following depletion of all CD8α+ lymphocytes." (PMID 39912921, 2025).
lung carcinoma (2 papers, 2021 to 2024). "Mutations in CD8B were associated with an increased lung cancer risk (OR = 3.2477, 95% CI: 1.0978–9.6079), while mutations in TRGV9 were linked to a reduced risk (OR = 0.3977, 95% CI: 0.2313–0.6837)." (PMID 38297377, 2024). "We explored the association between three genes, namely RNF125, CD8B, and TRGV9, and lung cancer risk." (PMID 38297377, 2024). "Immune C2, C3, and C6 had higher abundance of B cell and DC1, CD8A, CD8B, and hub genes, which indicated that immune C2, C3, and C6 lung cancer patients were suitable for immunotherapy and would benefit more from ICB therapy." (PMID 34422829, 2021). "In many respects, the high B cell/DC1 infiltration shaped an inflamed and immune-activated TME of lung cancer tissues, including adaptive immune resistance markers, CD8A, CD8B, immunomodulators (immunostimulants, MHC, receptors, and chemokines), and immune-related pathways." (PMID 34422829, 2021).
lymphopenia (2 papers, 2025). Reduction in the number of lymphocytes. "The effect at 5 dpi was driven by lymphopenia with a reduction of total T cells and particularly CD8β+ and CD8β−CD4−CD8α+ in both groups, and NK cells in farm pigs." (PMID 40557264, 2025). "This lymphopenia was followed by a sharp increase of T cells, in particular cytotoxic CD8β+ T cells at 14 dpi." (PMID 40557264, 2025).
malaria (2 papers, 2019 to 2020). Malaria is a serious and sometimes fatal disease caused by a parasite that commonly infects a certain type of mosquito which feeds on humans. "Interestingly, CD8+T cell depletion with a CD8β-specific monoclonal antibody almost fully preserved pulmonary epithelial integrity, suggesting that the damage induced by CD8+T cells can be prevented, as summarized in our proposed mechanism for malaria-associated ALI." (PMID 31534124, 2019).
myeloma (2 papers, 2021 to 2025). "Promising results have implied that usage of the dendritic/myeloma cell-based vaccine in the phase I/II trials conducts to an increase in the frequency of CD4b+ and CD8b+ myeloma specific T cells." (PMID 33781320, 2021).